CNTN6 (contactin 6)
Description:
Contactins mediate cell surface interactions during nervous system development. Participates in oligodendrocytes generation by acting as a ligand of NOTCH1. Its association with NOTCH1 promotes NOTCH1 activation through the released notch intracellular domain (NICD) and subsequent translocation to the nucleus. Involved in motor coordination (By similarity).
Synonyms: NB-3; NB3
Tractability: Antibody: UniProt places it where antibodies can reach, with medium confidence; UniProt predicts a signal peptide or a membrane-spanning region; its Gene Ontology location is reachable by antibodies, with medium confidence. PROTAC: its protein half-life has been measured.
Gene: Protein-coding gene on chromosome 3 (1,092,658 to 1,404,217, forward strand). Ensembl gene ENSG00000134115.
Subcellular location: Cell membrane
Pathways (Reactome):
Developmental Biology: CHL1 interactions
Gene Ontology:
Molecular function: cell-cell adhesion mediator activity
Biological process: axon guidance; cell adhesion; central nervous system development; dendrite self-avoidance; homophilic cell-cell adhesion; synapse organization
Cellular component: axon; plasma membrane; synapse; parallel fiber to Purkinje cell synapse; presynapse; presynaptic membrane
Genetic constraint (gnomAD): Loss-of-function variants: 110 observed, 97.92 expected, observed/expected ratio (o/e) 1.12, 90% interval 0.96 to 1.32. The synonymous counts are far from expectation, so gnomAD's model fits this gene poorly and the ratio says little. Missense variants: 1,412 observed, 1,098.6 expected, observed/expected ratio (o/e) 1.29, 90% interval 1.23 to 1.34. Synonymous variants: 503 observed, 388.37 expected, observed/expected ratio (o/e) 1.3, 90% interval 1.2 to 1.39.
Gene-disease validity (ClinGen):
ClinGen rates the evidence that CNTN6 causes each of these diseases.
complex neurodevelopmental disorder (autosomal dominant): Disputed. A disorder that involves more than one phenotype associated with the central nervous system, including but not limited to intellectual disability, autism, and seizures (epilepsy).
Homologues: Orthologues: chimpanzee CNTN6 (99% identical), macaque CNTN6 (97% identical), pig CNTN6 (92% identical), dog CNTN6 (92% identical), guinea pig CNTN6 (89% identical), rat Cntn6 (89% identical), mouse Cntn6 (89% identical), rabbit CNTN6 (81% identical). Paralogues in human: CNTN4 (60% identical), CNTN3 (59% identical), CNTN5 (50% identical), CNTN2 (43% identical), CNTN1 (41% identical), NRCAM (30% identical), L1CAM (28% identical), CHL1 (27% identical), NFASC (26% identical), DCC (23% identical), NEO1 (23% identical), ROBO1 (23% identical), and 24 more.
Diseases named in the same sentence as CNTN6 in open-access papers:
CNTN6 is named in the same sentence as 45 diseases in open-access papers, as found by Europe PMC text mining. Sharing a sentence is not in itself a finding about the gene and the disease. The quoted sentences say what the papers report.
Intellectual disability (10 papers, 2014 to 2025). "Various studies have implicated CNTN6, and more broadly contactins as a group, in metabolic, neurological, and mental health conditions, brain disorders, intellectual disability, depression, and AD-related traits." (PMID 37719713, 2023). "Mutations of CNTN6 have been reported in patients with speech and language delays, intellectual disability, and atypical ASD." (PMID 36794006, 2020). "Copy number variations of the human CNTN6 gene, resulting from megabase-scale microdeletions or microduplications in the 3p26.3 region, are frequently implicated in neurodevelopmental disorders such as intellectual disability and developmental delay." (PMID 39850828, 2025). "CNTN6 encodes a cell adhesion molecule, contactin-6, and has been implicated in ASD and intellectual disability." (PMID 34573303, 2021). "Similar to other CNVs involving synaptic and neurodevelopmental genes, the CNVs disrupting the CNTN6/CNTN4 region have also been reported in patients with intellectual disabilities, cognitive disorders, severe anorexia nervosa, and bipolar disorder in addition to ASD." (PMID 26257835, 2015). "CNTN6 duplications were first identified in patients with ASD2, 1,22 and later in a patient with intellectual disabilities and facial dysmorphisms." (PMID 29693535, 2018).
autism (7 papers, 2014 to 2023). Persistent deficits in social interaction and communication and interaction as well as a markedly restricted repertoire of activity and interest as well as repetitive patterns of behavior. "This conclusion was supported by in vivo analyses of the Cntn6-/- mouse brain displaying increased apoptosis which links Cntn6 to one of the pathogenic pathways of autism." (PMID 28018171, 2016). "In contrast to the BBGRE database, the phenotype for autism is rarely indicated, but several patients carrying CNTN6 deletions have cognitive impairments, ID or ASD." (PMID 27166760, 2017). "We report two siblings with ID and an unrelated patient with atypical autism who had 3p26.3 microdeletions and one intellectually disabled patient with a 3p26.3 microduplication encompassing only the CNTN6 gene." (PMID 25606055, 2014). "An isolated de novo duplication of the first two CNTN6 exons in a patient with an autistic disorder was also reported by van Daalen and colleagues." (PMID 25606055, 2014). "Currently, CNTN4, CNTN5, and CNTN6 are suggested as potential disease genes for autism." (PMID 24756565, 2014). "Thus, Cntn6 may also link to the Nrxn1-Nlgn1 pathway of autism through interaction with Lphn1." (PMID 28018171, 2016). "Very recently, as many observations have associated a number of synapse-related genes in the genesis of autism and other neuropsychiatric conditions, we have examined the expression of synaptophysin 1 (SYP1) and contactin 6 (CNTN6) in the vermis of reln+/− and reln+/+ adult mice of both genders." (PMID 31805691, 2019). "A loss of CNTN5 co-segregated with autism in one family, and one de novo CNV and one non-cosegregating inherited CNV in CNTN6 were found in a Utrecht cohort." (PMID 24756565, 2014).
autism spectrum disorder (7 papers, 2015 to 2023). A spectrum of developmental disorders that includes autism, and Asperger syndrome. "Mutations of CNTN5 and CNTN6 have previously been reported in individuals with autism spectrum disorders (ASDs), but very little is known on their prevalence and clinical impact." (PMID 27166760, 2017). "Copy number changes of close family members CNTN4, CNTN5, and CNTN6 have been associated with autism spectrum disorders." (PMID 28126037, 2017). "SNVs in CNTN6 are significantly associated with Autism spectrum disorder in particular." (PMID 35536790, 2022). "In view of important neurobiological functions of the cell adhesion molecule contactin-6 (Cntn6) that have emerged from studies on null-mutant mice and autism spectrum disorders patients, we set out to examine pathways underlying functions of Cntn6 using a proteomics approach." (PMID 28018171, 2016). "A role of Cntn6 in brain development is further emphasized by genetic findings of copy number variations (CNVs) in the human CNTN6 gene in rare cases with autism spectrum disorder (ASD)." (PMID 28018171, 2016). "Thirteen of the 14 patients with these CNTN6 copy number variations presented with various neurodevelopmental disorders including developmental delay, autistic spectrum disorders, seizures and attention deficit hyperactivity disorder." (PMID 26257835, 2015).
schizophrenia (5 papers, 2017 to 2025). A major psychotic disorder characterized by abnormalities in the perception or expression of reality. "On the other hand, the relationship between epilepsy and variations in the contactin-6 gene (CNTN6) remains scarce, but a deletion of exons 21 and 22 has been highly associated with the presence of schizophrenia and seizures (which is the hallmark symptom of epilepsy)." (PMID 31354411, 2019).
epilepsy (4 papers, 2017 to 2020). A brain disorder characterized by episodes of abnormally increased neuronal discharge resulting in transient episodes of sensory or motor neurological dysfunction, or psychic dysfunction. "However, there is a significant interest in the study of new variants related to epilepsy among them neurexins and contactin-6, ligands that interact with latrophilins." (PMID 31354411, 2019). "In particular, genes such as ANXA1, CNTN6, HLA-B, PCDH19, and PCDH10, have been linked to ASD, epilepsy, ID, and other neuropsychiatric disorders, were significantly upregulated or downregulated and warrant further investigation." (PMID 31921404, 2020).
bipolar disorder (3 papers, 2011 to 2018). A disorder of the brain that causes unusual shifts in mood, energy, activity levels and the ability to carry out day-to-day tasks. "Bipolar disorder with alcohol dependence and other co-morbidities was associated with SNP rs2727943 (p = 3.3×10−8) on chromosome 3p26.3 located between the genes contactin-4 precursor (BIG-2) and contactin 6 (CNTN6)." (PMID 22205951, 2011). "In family 13, the asymptomatic father has normal copy number for CNTN6; the proband with ADHD and bipolar disorder inherited the duplication of CNTN6 from the mother who has psychiatric problems." (PMID 26257835, 2015).
Cognitive impairment (3 papers, 2015 to 2025). Abnormal cognition is characterized by deficits in thinking, reasoning, or remembering. "The 3p deletion involved four pathogenic genes (CHL1, CNTN6, CNTN4, ITPR1) associated with cognitive impairment, ataxia, and motor dysfunction." (PMID 41384039, 2025).
microcephaly (3 papers, 2014 to 2025). A congenital or acquired developmental disorder in which the circumference of the head is smaller than normal for the person's age and sex. "Deletions of both CNTN4 and CNTN6 genes have been reported in the 3p deletion syndrome, which is characterized by low birth weight, growth restriction, DD, ID, hypotonia, and microcephaly." (PMID 26257835, 2015). "Furthermore, microcephaly was also reported in two previously reported patients with deletion of CNTN6." (PMID 26257835, 2015).
prostate carcinoma (2 papers, 2017 to 2022). A carcinoma that arises from epithelial cells of the prostate gland. "Other potentially clinically relevant genes with single base somatic mutations include NOTCH2, recently proposed as an oncogene in bladder cancer, with the Notch family pathway implicated in prostate tumorigenesis, and CNTN6 within the 3p26 prostate cancer susceptibility locus." (PMID 28423598, 2017). "In the prostate cancer cohort, the mutation frequencies of ARID2, CNTN6, CHD1 and other genes were significantly different in different IP-score groups." (PMID 36700205, 2022).
breast carcinoma (1 paper, 2015). "3p would include TGFBR2, CNTN4, and CHL1 (reported for colorectal cancer) and CNTN6 (for breast cancer), as well as FHIT, ROBO1-GRE1 and SETMAR-LRRN1." (PMID 26247464, 2015).
Cerebral ischemia (1 paper, 2019). Restriction of arterial blood supply to the brain associated with insufficient oxygenation to support the metabolic requirements of the tissue. "For instance, the formation and terminal branching of the corticospinal tract is delayed in CNTN6-null mice, and neurite growth and neuronal survival is impaired in CNTN6-null mice with cerebral ischemia, aggrevating ischemic damage." (PMID 31297045, 2019).
Dandy-Walker malformation (1 paper, 2016). "Furthermore, our data suggests the involvement of CNTN6 and KLHL15 in the etiology of agenesis of the corpus callosum, the involvement of RASD1 and PTPRD in Dandy-Walker malformation, and the involvement of ERMARD in ventriculomegaly." (PMID 27087860, 2016).
melanoma (1 paper, 2024). A malignant, usually aggressive tumor composed of atypical, neoplastic melanocytes. "In conclusion, this study provides insight into the potential mechanisms underlying Si162 resistance in melanoma cells and identified 5 genes (CNTN6, ADD1, FGF18, C18orf25, and RPL13) as potential prognostic biomarkers for Si162 resistance." (PMID 38665777, 2024).
memory impairment (1 paper, 2018). "Our results show that Cntn6 mutant mice exhibit sexual difference in spatial learning and memory impairments." (PMID 30106251, 2018).
psychosis (1 paper, 2021). "More research is needed to further elucidate the role of MACF1 in psychosis as well as its interaction with CNTN6 and CDH13." (PMID 33897758, 2021). "Besides, our results confirm previous results suggesting the involvement of MACF1, CNTN6, and CDH13 in the etiology of psychosis." (PMID 33897758, 2021).
neurodevelopmental disorder (10 papers, 2014 to 2025). A behavioral and cognitive disorder with onset during the developmental period that involves impaired or aberrant development of intellectual, motor, or social functions. "Since CNTN6 has been implicated in neurodevelopmental disorders we set out to examine pathways of action of this contactin member." (PMID 28018171, 2016). "CNTN6, as well as other members of this protein family, have been identified as potential disease-causing genes in neurodevelopmental disorders." (PMID 25606055, 2014). "Duplications of chromosome 3p that include contactin genes CNTN6 and CNTN4 have been reported to be associated with neurodevelopmental disorders." (PMID 40760574, 2025). "It is important to note that no additional abnormalities were found in the CNTN6 gene or its regulatory regions.We assume that the duplication of CNTN6 leads to the development of neurodevelopmental disorders through a decrease in the gene expression." (PMID 39850828, 2025). "The observed similarities in neurodevelopmental disorders among patients with microdeletions and microduplications of the CNTN6 gene were clarified in our previous experiments using induced pluripotent stem (iPS) cells (iPS cells)." (PMID 39850828, 2025). "Among 14 patients with deletions (seven cases) or duplications (five cases) involving only the CNTN6 gene or its fragments, eleven exhibited neurodevelopmental disorders, and six displayed dysmorphic features." (PMID 39850828, 2025). "The homozygous SNV in CNTN6 shared among affected members of pedigree 10 with consanguineous marriage is also interesting, as several recent reports have identified CNTN6 as a candidate gene involved in neurodevelopmental disorders, including SCZ." (PMID 35536790, 2022). "Genes implicated in ASD such as Annexin 1 (ANXA1), HLA-B and CNTN6 with deletion or duplication in a spectrum of neurodevelopmental disorders and ID were upregulated in TSC1-Het and Null NPCS when compared with the WT." (PMID 31921404, 2020). "For instance, among 14 patients carrying deletions (7 cases) or duplications (5 cases) involving only the CNTN6 gene, eleven had neurodevelopmental disorders, and six had dysmorphic features." (PMID 29297312, 2017). "These genotype phenotype correlations pave the way to further investigate the role of CNTN6 in neurodevelopmental disorders." (PMID 26257835, 2015). "We present here 13 of the 14 patients with neurodevelopmental disorders and CNVs in the 3p26.3 region encompassing the CNTN6 gene." (PMID 26257835, 2015). "CNTN6 and CNTN4 encode for contacting proteins, which mediate cell surface interactions during nervous system development and have been suggested to be associated with neurodevelopmental disorders, though the association with nephrotoxicity needs to be further explored." (PMID 32617516, 2020). "However, duplication of the full-length human CNTN6 gene presents with variable penetrance, resulting in phenotypes that range from neurodevelopmental disorders to no visible pathologies, even within the same family." (PMID 39850828, 2025).
cancer (6 papers, 2015 to 2025). A tumor composed of atypical neoplastic, often pleomorphic cells that invade other tissues. "Among the nine selected cancer associated genes with germline variants SMARCB1 was downregulated and so was CNTN6, whereas MYCL was upregulated." (PMID 26998479, 2015).
CNTN6 also shares sentences with these, for which no sentence is quoted: attention deficit-hyperactivity disorder (2 papers); developmental delay (2); tumor (2); alcohol dependence (1); Alzheimer disease (1); amyloid (1); anorexia nervosa (1); Aphasia (1); Ataxia (1); atherosclerosis (1); Autoimmunity (1); bladder cancer (1); brain disorder (1); carcinoma of the gall bladder (1); cardiovascular diseases (1); cognitive disorder (1); colorectal cancer (1); depression (1); Duchenne muscular dystrophy (1); dyslexia (1); language delays (1); monocytic leukemia (1); neuroblastoma (1); psychiatric disorder (1); tongue tumors (1); Tourette syndrome (1); type 2 diabetes (1); Ventriculomegaly (1).